CRHR1 (corticotropin releasing hormone receptor 1)
Diseases named in the same sentence as CRHR1 in open-access papers (continued):
Sharing a sentence is not in itself a finding about the gene and the disease.
endometriosis (continued). "Despite the fact that CRH/UCN have been implicated in endometriosis – a fact also verified by our results, no data has been reported so far concerning the expression of CRHR1 and CRHR2, the CRH and UCN receptors." (PMID 23638035, 2013). "Also, the role of CRHR1 in the autocrine/paracrine pathway of eutopic and ectopic endometrium has been demonstrated, which is suggested to potentially affect the pathogenesis of endometriosis and the infertility profile of affected women." (PMID 38012716, 2023). "Therefore, mechanisms initiated via CRHR1 signaling deserve increased attention in endometriosis and might be similar to those that have been previously implicated in IBS development." (PMID 30427841, 2018). "Given the fact that we observed an increase in mRNA in both, CRHR1 and CRHR2, in rats with endometriosis that received vehicle, we can infer that catecholamine secretion is also altered due to endometriosis." (PMID 31935235, 2020). "Finally, based on these results, showing that the CRH upregulative effect on galectin-1 is mediated by CRHR1, the potential use of Antalarmin could be reinforced in accessing the immune disequilibrium noticed in eutopic and ectopic endometrium of women with endometriosis." (PMID 25473847, 2014). "Further mechanistic experiments and experiments on appropriate models needs to be done in order to clarify this role and highlight a potential use of anti-CRHR1 and anti-CRHR2 treatment in endometriosis." (PMID 23638035, 2013). "We further compared the expression of CRH, UCN, CRHR1 and CRHR2 in ectopic endometrium to that in eutopic endometrium of women with endometriosis." (PMID 23638035, 2013). "CRH, UCN, CRHR1 and CRHR2 mRNA were also more highly expressed in ectopic rather than eutopic endometrium (CRH, UCN, CRHR2α: p<0.01, CRHR1β: p<0.05) and protein (CRH and UCN: p<0.05, CRHR1 and CRHR2: p<0.01) in women with endometriosis." (PMID 23638035, 2013). "Despite the well-documented role of the CRH receptor in stress related disorders, reproductive function and inflammation, no previous study has addressed the potential role of CRHR1 blockade in the treatment of endometriosis." (PMID 30427841, 2018). "Interestingly, we found that the expression of CRH, UCN and their receptor subtypes, CRHR1 and CRHR2 is stronger in ectopic endometrium compared to that in eutopic endometrium of women with endometriosis." (PMID 23638035, 2013). "This adds support to the hypothesis that there is a dysregulation of the HPA axis during endometriosis progression, which was not completely reversed by pharmacological manipulation with the CRHR1 antagonist antalarmin." (PMID 31935235, 2020). "Additional CRHR1 antagonists that do not enter the blood brain barrier might be an effective tool to test in the endometriosis rat model." (PMID 30427841, 2018). "Unidentified endometrial defects in endometriosis could also affect the expression of CRH and UCN resulting in increased expression of CRHR1 and CRHR2 acting as a regulatory mechanism to compensate for the reduced efficiency of proper endometrial function of endometriotic women." (PMID 23638035, 2013). "This is the first time a study shows that CRHR1 and CRHR2 and specifically the CRHR1β and CRHR2α receptor subtypes are expressed at mRNA and protein level, not only in the endometrium but also at endometriotic sites indicating a potential crucial role of CRH and UCN in endometriosis." (PMID 23638035, 2013). "We compared the expression levels of CRHR1 and CRHR2 in eutopic endometrium of endometriotic women with that in eutopic endometrium of healthy women to further examine the implication of these molecules in endometriosis and the infertility profile of endometriotic women." (PMID 23638035, 2013). "CRH, UCN, CRHR1 and CRHR2 mRNA were also more highly expressed in ectopic rather than eutopic endometrium in women with endometriosis." (PMID 25473847, 2014).
panic disorder (8 papers, 2013 to 2023). An anxiety disorder characterized by multiple unexpected panic attacks with persistent concern of recurring attacks. "Similar findings were observed in peripheral blood samples of patients diagnosed specifically with panic disorder, making Crhr1 hypomethylation a possible diagnostic marker for panic disorder and other ADs." (PMID 35998298, 2023). "There is converging evidence that s-carriers of 5HTTLPR are at risk for anxious personality and symptomology, and presence of the G-allele of CRHR1 (rs878886) has been linked to panic disorder in a recent study that included a replication sample." (PMID 23717480, 2013). "Most notably, a single nucleotide polymorphism (rs878886) within the promoter region of CRHR1 has been linked to panic disorder." (PMID 23717480, 2013). "The hypomethylation in the promoter region of CRHR1 has the potential role of increasing CRHR1 expression as was identified in a case-control study of panic disorder." (PMID 32180791, 2020). "The results suggested that polymorphisms within CRHR1, on chromosome 17, and AVPR1B, on chromosome 1, genes had effect on susceptibility for panic disorder." (PMID 31435520, 2018). "More recent studies suggest the role of corticotropin releasing hormone receptor 1 (CRHR1) hypomethylation in panic disorder." (PMID 31435520, 2018). "The study compared healthy controls and the panic disorder patients and result showed relation with hypomethylation of CRHR1, in other words, increased expression of CRHR1 in the panic disorder patients." (PMID 31435520, 2018). "Two SNP pairs, AVPR1B rs28632197—CRHR1 rs878886 and AVPR1B rs28632197—CRHR1 rs187631, were also found to be significantly associated with panic disorder." (PMID 27920663, 2016).
schizophrenia (8 papers, 2013 to 2026). A major psychotic disorder characterized by abnormalities in the perception or expression of reality. "The association between CRHR1 and CRHBP genes with severity of suicidal behavior was found in patients with schizophrenia." (PMID 28358316, 2017). "Many genes that were found in this analysis, including CRHR1, ARL17A, NSF, and OGFOD2, have been implicated in previous GWAS of regional brain volumes, and have also been linked to brain disorders, including epilepsy, schizophrenia, and brain cancer." (PMID 39269986, 2024). "In addition, SMG9 in AD, TCTA in anorexia nervosa, RHOA and IMPDH2 in intelligence, CRHR1 in PD, and PHF7 in schizophrenia are all reported to be conserved among a wide range of species, although their relations with the corresponding traits remain to be explored." (PMID 39905509, 2025).
alcohol use disorder (7 papers, 2015 to 2022). "The CRHR1 gene is involved in the anxiogenic action of CRH, and studies have shown that the CRHR1 gene was associated with addiction vulnerability and modulated the effects of exposure to childhood abuse on addictive disorders such as alcohol use disorder." (PMID 30572854, 2018). "Additional gene variants of CRHR1 and CRHBP have been associated with various mood and anxiety disorders as well as alcohol use disorders [reviewed in Ref." (PMID 29497387, 2018). "Individual CRHBP and CRHR1 SNPs have been shown to coordinately predict alcohol use disorder comorbidity in a panel of schizophrenic patients." (PMID 29497387, 2018). "Additional study has shown the importance of CRHR1 in integrating gene—environment effects in alcohol use disorders." (PMID 25802844, 2015). "In the study period, the labels of the top ten clusters were: #0 NPY, #1 GLT-1, #2 acamprosate, #3 GABAA receptor subtypes, #4 EAAT2, #5 baclofen, #7 corticotropin releasing hormone receptor 1 (CRHR1), #8 alcohol use disorder, #9 C57BL/6, #10 COR659 (a GABAB positive allosteric modulator)." (PMID 36032235, 2022).
Cognitive impairment (7 papers, 2018 to 2026). Abnormal cognition is characterized by deficits in thinking, reasoning, or remembering. "Future research is needed to clarify the pathogenicity of CRHR1 genetic variations and underlying mechanisms of cognitive impairment in COVID-19 survivors and explore potential therapeutic strategies targeting both genetic and psychological factors." (PMID 41614899, 2026). "This raises an important research question: Can SARS-CoV-2, as a potent stressor, induce cognitive impairment in individuals harboring CRHR1 gene variations or mutations?”." (PMID 41614899, 2026). "Along these lines, forebrain-specific deletion of Crhr1 decreases the susceptibility to chronic stress-induced cognitive deficits." (PMID 31619956, 2019). "Alterations in the CRHR1 gene, including copy number variations, may be associated with dysregulation of stress-response pathways, which could increase vulnerability to cognitive impairment and depressive symptoms through different biological mechanisms." (PMID 41614899, 2026). "Wang X., Chen Y., Wolf M., Wagner K., Liebl C., Scharf S., Harbich D.,Mayer B., Wurst W., Holsboer F., Deussing J., Baram T., Müller M.,Schmidt M. Forebrain CRHR1 deficiency attenuates chronic stressinduced cognitive deficits and dendritic remodeling." (PMID 34901719, 2021). "This study aimed to investigate the role of CRHR1 gene CNVs in objectively measured cognitive impairment and self-reported cognitive decline following SARS-CoV-2 infection." (PMID 41614899, 2026). "CNVs in the CRHR1 gene were examined to assess their potential relationship with objective and subjective cognitive impairment." (PMID 41614899, 2026). "In this sense, the normalization of Crh, Crhr1, and Egr1 mRNA levels by social support may be involved in the stress-induced cognitive impairments." (PMID 30104581, 2018). "Interestingly, while CRHR1 gene CNVs were significantly associated with objective cognitive impairments, they did not appear to influence self-reported cognitive decline (see details below)." (PMID 41614899, 2026). "Therefore, elucidating the links between CRHR1 genetic alterations and cognitive impairment may be important for identifying vulnerable individuals and informing future preventive or therapeutic strategies, particularly in populations exposed to chronic stress or neuroinflammatory insults." (PMID 41614899, 2026). "In addition, because all participants were SARS-CoV-2-positive, the study design allows evaluation of CRHR1 CNVs as potential modifiers of post-COVID-19 cognitive impairment but does not permit conclusions regarding whether these CNVs are specifically related to SARS-CoV-2 infection." (PMID 41614899, 2026).
COVID-19 (7 papers, 2021 to 2026). A disease caused by infection with severe acute respiratory syndrome coronavirus 2. "An intronic variation in CRHR1 (rs61667602-T) had reduced risk for severe COVID-19 (OR= 0.91) as well as respiratory conditions such as IPF." (PMID 34642702, 2021). "While that study does not address cognition or CRHR1 directly, it reinforces the importance of considering immune dysregulation as a factor potentially interacting with genetic predispositions in post-COVID-19 neuropsychiatric symptoms." (PMID 41614899, 2026). "These immune signatures, although not directly linked to cognition or CRHR1 in the existing literature, support the broader hypothesis that immune dysregulation interacts with genetic predisposition in shaping neuropsychiatric symptoms after COVID-19." (PMID 41614899, 2026). "Among these overlapping genes, nonsynonymous SNPs in the exons across SPPL2C, CRHR1, MAPT, STH, and KANSL1 genes were identified, among which, 13 were from COVID-19 critical illness and 15 were from COVID-19 hospitalization." (PMID 39764106, 2024).
breast carcinoma (6 papers, 2009 to 2024). "A previous prospective study found the contribution of geneticvariants in hypothalamic-pituitary-adrenal (HPA) axis genes including CRHR1 to therisk of developing breast cancer, which was consistent with our result." (PMID 38626574, 2024).
hypercortisolism (6 papers, 2017 to 2025). "In conclusion, we reported a mutation in CRHR1 that leads to persistent activation of the receptor in a poodle with PDH, indicating that this is a rare cause of ACTH-dependent hypercortisolism." (PMID 29069262, 2017). "In conclusion, CRHR1- and CRHR2-risk variants might confer pleiotropic effects, some specific to PCOS, and some related to hypercortisolism, T2D, and MDD." (PMID 37543650, 2023). "However, CRHR1- and CRHR2-risk variants might also lead to hypercortisolism and confer mental-metabolic pleiotropic effects." (PMID 37543650, 2023). "Interestingly, increased methylation of SNPs in the FKBP5 gene (e.g., rs9296158) and some CRHR1 gene polymorphisms that produce high levels of CRH are associated with cortisol hypersensitivity and hypercortisolism and represent a distinct PTSD phenotype from that characterized by hypercortisolism." (PMID 37374323, 2023). "Dysfunctional CRH receptor 1 (CRHR1) and CRH receptor 2 (CRHR2), both of which are involved in glucose regulation, may explain hypercortisolism in MDD and T2D, at least in a subgroup of patients." (PMID 38927393, 2024).
Parkinson disease (6 papers, 2013 to 2025). A progressive degenerative disorder of the central nervous system characterized by loss of dopamine producing neurons in the substantia nigra and the presence of Lewy bodies in the substantia nigra and locus coeruleus. "Variation in this region has been associated with Parkinson's disease (MAPT, PLEKHM1, NSF, c17orf69) progressive supranuclear palsy (MAPT), celiac disease (WNT3), bone mineral density (CRHR1) (NHGRI GWAS catalog) and intracranial volume." (PMID 23544013, 2013). "Meanwhile, six genes near MAPT in chromosome 17 including MAPT-AS1, SPPL2C, CRHR1, KANSL1, NSF, and WNT3 have been identified as risk genes by earlier GWAS for Parkinson’s disease, another common neurodegenerative disorder which might present clinical symptoms of FTD." (PMID 35509074, 2022).
post-traumatic stress disorder (6 papers, 2020 to 2026). An anxiety disorder precipitated by an experience of intense fear or horror while exposed to a traumatic (especially life-threatening) event. "Exploratory work in post-traumatic stress disorder suggests that lower baseline CRHR1 methylation and treatment-related demethylation track greater symptom improvement under CRF1 blockade, hinting that epigenetic or inflammatory stratifiers could identify responder subgroups." (PMID 41373485, 2025).
irritable bowel syndrome (5 papers, 2012 to 2023). Irritable bowel syndrome (IBS) is a chronic functional condition of the lower gastrointestinal (GI) tract characterized by abdominal pain or discomfort and disordered bowel habit (diarrhea, constipation, or fluctuation between the two). "SNPs in CRHR1 are shown to contribute to the development of irritable bowel syndrome (IBS)." (PMID 32244319, 2020).
ovarian carcinoma (5 papers, 2007 to 2024). A malignant neoplasm originating from the surface ovarian epithelium. "Regarding the molecular mechanism, the authors provided evidence that CRH acts on ovarian cancer through CRHR1, which upregulates the expression of Fas ligands (FasL), potentiating the ability to induce Fas-mediated apoptosis." (PMID 36552294, 2022). "Moreover, our study providednew evidence to support previous studies on the role of CRHR1 in tumorigenesisprogression of breast and ovarian cancer." (PMID 38626574, 2024). "Indeed, CRH acted on the ovarian cancer cells OvCa3 and A2780, through CRHR1, to upregulate the expression of FasL and thus potentiate the ability of the cells to induce Fas-mediated apoptosis of activated PBL." (PMID 17667919, 2007). "It is tempting to speculate that in advanced stage ovarian carcinoma, chronic use of a CRHR1 antagonist could reduce tumour immune defence mechanisms by downregulating intratumoral FasL expression." (PMID 17667919, 2007). "Among them, 306 gene–tissue pairs are overlapped for the breast–ovarian cancer pair, and the tissues involved are scattered; however, a number of genes are almost concentrated in the clumping region of rs4277389 on chromosome 17, such as CRHR1, LRRC37A, and MAPT." (PMID 36819030, 2023). "Therefore, it is tempting to hypothesize that CRHR1 antagonists could constitute a rational pharmacological target to treat ovarian cancer." (PMID 36552294, 2022). "Here, we examined immunohistochemically the expression of CRH, CRHR1, CRHR2 and FasL in 47 human ovarian cancer cases." (PMID 17667919, 2007). "In the present study, we examined the distribution of CRH, CRHR1, CRHR2 and FasL peptides in ovarian carcinoma and we investigated the potential role of CRH and FasL in modulating the immune defenses of ovarian cancer cells." (PMID 17667919, 2007).
adenoma (4 papers, 2017 to 2021). A neoplasm arising from the epithelium. "In contrast, the percentage proportions of large adenoma (>4 mm diameter) and medium-sized adenoma (2–4 mm) were markedly increased in Crhr2−/− mice compared to those of Crhr1+/+ mice." (PMID 33494263, 2021). "Among various genes associated with tumorigenesis, we found that the expression of Cox2 is dramatically reduced in tumors of Apcmin/+; Crhr1−/− mice and Apcmin/+; Crhr1+/− mice, compared to the expression in adenomas from Apcmin/+; Crhr1+/+ mice." (PMID 33494263, 2021). "The percentage proportions of large adenoma (> 4 mm diameter) and medium-sized adenoma (2–4 mm) were greatly reduced in Apcmin/+; Crhr1−/− mice compared to those of littermate Apcmin/+; Crhr1+/− and Apcmin/+; Crhr1+/+ mice." (PMID 33494263, 2021). "However, the mRNA levels of tumor-associated genes, including Vegf-a, interleukin 6 (Il6), and tumor necrosis factor α (Tnfα), were comparable in all adenomas from Apcmin/+; Crhr1−/−, Apcmin/+; Crhr1+/−, and Apcmin/+; Crhr1+/+ mice." (PMID 33494263, 2021). "Furthermore, we observed that the mRNA expression of Pla2 is markedly increased in adenomas of Apcmin/+; Crhr1−/− mice and Apcmin/+; Crhr1+/− mice, compared to the level of Apcmin/+; Crhr1+/+ mice." (PMID 33494263, 2021). "Another hypothesis is that the affected dog, by carrying a CRHR1 activating mutation, developed only pituitary hyperplasia and not an adenoma." (PMID 29069262, 2017). "Accordingly, the histological analysis exhibited that either Crhr1 or Crhr2 deletion does not alter the histopathological nature of adenomas developed in Apcmin/+ mice." (PMID 33494263, 2021).
endometrial cancer (4 papers, 2012 to 2020). Primary or metastatic malignant neoplasm involving the endometrium (mucous membrane that lines the endometrial cavity). "Accordingly, CRH was found to induce cAMP in human endometrium via CRHR1 triggered protein-kinase A (PKA) and we recently found that Syn1 is induced via the cAMP pathway in endometrial carcinoma." (PMID 22971074, 2012).
mental disorder (4 papers, 2015 to 2025). A disease that has its basis in the disruption of mental process. "Hence, the physical interaction of CRHR1 with multiple MAGUKs suggests that some of the emotional disturbances observed across mental disorders could be linked to impaired CRHR1 function." (PMID 26352593, 2015). "In summary, we used an interdisciplinary approach of human genetics and clinical phenotyping of T2D with MDD and pioneered the joint study of a neuro-endocrine stress-related gene, CRHR1, in human T2D and MDD, a metabolic and mental disorder, whose pathogenesis might be shared." (PMID 38092990, 2025).
stress-related disorder (4 papers, 2015 to 2024). Stress-related disorders are mental health disorders that are a result of an atypical response to both short and long-term anxiety due to physical, mental, or emotional stress. "There have already been studies based on CRHR1 antagonism as a potential therapy for stress-related disorders, but unfortunately, they have failed before translation into clinical practice." (PMID 39595978, 2024).